SHFL (shiftless antiviral inhibitor of ribosomal frameshifting)
Description:
Inhibits programmed -1 ribosomal frameshifting (-1PRF) of a variety of mRNAs from viruses, such as HIV1, and cellular genes, such as PEG10. Interacts with the -1PRF signal of target mRNA and translating ribosomes and causes premature translation termination at the frameshifting site. Regulates HIV1 GAG-POL expression by inhibiting -1PRF. Exhibits antiviral activity against dengue virus (DENV) and can inhibit the replication of all DENV serotypes. May block the protein translation of DENV RNA via its association with cellular mRNA-binding proteins and viral RNA. Also interrupts Zika virus replication by promoting viral NS3 degradation via a lysosome-dependent pathway. Can also limit the replication of hepatitis C virus (HCV) by restricting formation of viral replication organelle, West Nile virus (WNV), Chikungunya virus (CHIKV), herpes simplex virus type 1 (HHV-1), herpes virus type 8 (HHV-8) and human adenovirus. Binds nucleic acids with a higher affinity for ssRNA and ssDNA than for dsDNA. Isoform 4 does not inhibit programmed ribosomal frameshifting (-1PRF). Does not bind to ribosomes.
Synonyms: SFL; IRAV; RyDEN; C19orf66; FLJ11286
Tractability: PROTAC: ubiquitination databases record sites on it.
Gene: Protein-coding gene on chromosome 19 (10,086,122 to 10,093,252, forward strand). Ensembl gene ENSG00000130813.
Subcellular location: Cytoplasm; Nucleus; Cytoplasm, P-body
Subcellular location (Human Protein Atlas): Nucleoplasm; Cytosol
Gene Ontology:
Molecular function: protein binding; ribosome binding; RNA binding; sequence-specific mRNA binding
Biological process: defense response to virus; negative regulation of translational frameshifting; negative regulation of viral genome replication; regulation of translational termination; response to interferon-beta; response to type I interferon; response to type II interferon; response to type III interferon; viral translational frameshifting; innate immune response
Cellular component: cytoplasm; cytosol; nucleoplasm; nucleus; P-body
Genetic constraint (gnomAD): Loss-of-function variants: 13 observed, 32.27 expected, observed/expected ratio (o/e) 0.4, 90% interval 0.26 to 0.64. The upper end of that interval is the gene's LOEUF score, 0.64, which puts it in group 2 of 6, group 1 being the genes least tolerant of losing a copy. Missense variants: 278 observed, 402.79 expected, observed/expected ratio (o/e) 0.69, 90% interval 0.62 to 0.76. Synonymous variants: 148 observed, 154.62 expected, observed/expected ratio (o/e) 0.96, 90% interval 0.84 to 1.1.
Homologues: Orthologues: chimpanzee SHFL (100% identical), mouse Shfl (95% identical), rabbit SHFL (95% identical), dog SHFL (94% identical), pig SHFL (90% identical), guinea pig SHFL (87% identical), macaque SHFL (78% identical), rat Shfl (76% identical), tropical clawed frog shfl (56% identical), zebrafish shfl (51% identical).
Diseases named in the same sentence as SHFL in open-access papers:
SHFL is named in the same sentence as 12 diseases in open-access papers, as found by Europe PMC text mining. Sharing a sentence is not in itself a finding about the gene and the disease. The quoted sentences say what the papers report.
viral infection (7 papers, 2010 to 2026). "Here, we provide a comprehensive review of the many mechanisms by which SHFL restricts viral infection, the consequences of its many functions on the regulation viral and host RNA fate, and the implications of SHFL role as a critical piece of the innate immune response to viral infection." (PMID 35746809, 2022). "Of note, there is also a correspondingly low level of SHFL protein in the liver which could suggest significant post-transcriptional regulatory mechanisms that restrict the expression of SHFL outside the context of viral infection, perhaps due to cytotoxicity as has been previously reported." (PMID 35746809, 2022). "An increasing number of large-scale screens have independently identified SHFL as both an anti-viral factor and downstream effector of the Type I, II, and III interferon response to viral infection." (PMID 35746809, 2022). "Taken together, our observations suggest a role of SHFL in inhibiting PB formation to restrict KSHV lytic replication, reinforcing the importance of crosstalk between RNA fate and the innate immune response to viral infection." (PMID 41824329, 2026). "Unusually, and in contrast to selected classical IRGs, human and mouse SHFL orthologues (hSHFL and mSHFL, respectively) were highly expressed in hepatocytes in the absence of viral infection, weakly induced by IFN, and highly conserved at the amino acid level (>95%)." (PMID 37341610, 2023). "Hanners and colleagues further explored the mechanism by which SHFL restricts HCV and YFV replication and found that, similar to DENV, SHFL binds to viral RNA, does not affect primary translation, but was still capable of restricting later stages of viral infection." (PMID 35746809, 2022).
ZIKV infection (3 papers, 2020 to 2023). "SHFL knockout animals are viable and exhibit enhanced susceptibility to ZIKV infection." (PMID 37341610, 2023).
Flavivirus Infections (1 paper, 2022). Infections with viruses of the genus FLAVIVIRUS, family FLAVIVIRIDAE. "The KO mice would be a powerful model to analyze the inhibitory role of SHFL in other flavivirus infections in vivo." (PMID 36293480, 2022). "In this review, we summarize the current understanding of the molecular mechanisms by which SHFL inhibits flavivirus infection and discuss the molecular basis of the inhibitory mechanism using a predicted tertiary structure of SHFL generated by the program AlphaFold2." (PMID 36293480, 2022). "Therefore, it can be proposed that, upon flavivirus infection, SHFL and MOV10 are recruited from the P-body to the region where the flaviviral RNA amplification process takes place and collaborate to induce the destabilization of viral RNA." (PMID 36293480, 2022).
influenza (1 paper, 2022). An acute viral infection of the respiratory tract, occurring in isolated cases, in epidemics, or in pandemics; it is caused by serologically different strains of viruses (influenzaviruses) designated A, B, and C, has a 3-day incubation period, and usually lasts for 3 to 10 days. "Taken together, these observations warrant further studies into CMTR1 and SHFL as potential influenza virus host factors and targets to modulate influenza pathogenicity." (PMID 36713229, 2022).
infection (9 papers, 2010 to 2025). The state of being infected such as from the introduction of a foreign agent such as serum, vaccine, antigenic substance or organism. "SHFL (shiftless antiviral inhibitor of ribosomal frameshifting) is a novel ISG that inhibits dengue virus (DENV), West Nile virus (WNV), Zika virus (ZIKV), and Japanese encephalitis virus (JEV) infections." (PMID 36293480, 2022). "Importantly, infection by other hemorrhagic and encephalitic flaviviruses, including WNV, YFV, JEV, and ZIKV, was found to be inhibited by the expression of SHFL, suggesting that SHFL is a pan-flaviviral cellular inhibitor." (PMID 36293480, 2022). "Further investigation into the SHFL inhibitory mode of action revealed that SHFL expression significantly restricted the accumulation of DENV RNA in infected cells between 18 and 24 h post infection." (PMID 35746809, 2022). "While not often consistent from one infection context to the next, further investigation of how SHFL regulates both viral and host mRNA along the axis of RNA stability and translation will likely prove to be essential for one or more of the mechanisms discussed here." (PMID 35746809, 2022).
SHFL also shares sentences with these, for which no sentence is quoted: HIV-1 infection (4 papers); cancer (3); infectious disease (2); cervical carcinoma (1); cutaneous melanoma (1); dengue virus infection (1); skin cancer (1).